IL6 (interleukin 6)
Diseases named in the same sentence as IL6 in open-access papers (continued):
Sharing a sentence is not in itself a finding about the gene and the disease.
tumor (continued). "The sources of salivary IL6 in patients with OSCC were investigated using paired tumour tissues and saliva samples, where tumour tissue and tumour-infiltrating leukocytes were positively stained for IL6, indicating production of IL6." (PMID 36900301, 2023). "Some reports suggest that IL-17 promotes tumor growth by inducing IL-6 production to activate IL-6-Stat3 signaling." (PMID 38062130, 2023). "Tumor cells exposed to IL-6 activate the oncogenic STAT3 transcription factor to promote epithelial-to-mesenchymal transition (EMT), which is the first step for tumor cell migration." (PMID 36891151, 2023). "In the tumor microenvironment, IL-6/JAK/STAT3 signaling pathway drives malignant cell proliferation, survival, invasion, and metastasis while strongly inhibiting the antitumor immune response." (PMID 36937841, 2023). "In that study, during the treatment similar increases were also seen in inflammatory markers (such as interleukin-6 (IL-6)) in the group with HPV-related tumours." (PMID 37835558, 2023). "IL-6 is highly expressed in the matrix of many malignant tumors, so it is an important factor in the relationship between inflammation and tumor." (PMID 36845384, 2023). "Tumor cells and surrounding stroma are responsible for the synthesis of IL-6, which induces inflammation via PI3K, Ras/Raf/MAPK, or Src/YAP pathways through JAK." (PMID 37511415, 2023). "This is mediated by the involvement of tumor-derived exosomes (TDEs) with low let-7s that mediate the production of cytokines (IL-6, IL-10) and induce N2 transformation." (PMID 37153744, 2023). "IL-6 further induces a reciprocal cytokine network in tumor tissues, including IL-8, GM-CSF, and VEGF, which supports angiogenesis and leads to the recruitment of immunoregulatory cells that enable tumor progression." (PMID 36816953, 2023). "Our data suggest that not only IL-6, but also immune cells, such as MDSCs and CD8+ cells, in peripheral blood are associated with the tumor microenvironment and patient outcome." (PMID 37733188, 2023). "The most likely explanation for the reduced levels of IL-6 in the presence of tumor cells is increased consumption of the cytokine." (PMID 36913398, 2023). "In this regard, irradiated tumor-cell-derived EVs containing large amounts of DAMPs increased the expression of iNOS, IL-1, IL-6, IL-12, TNF-α and IFN-γ and modified the TME." (PMID 37175226, 2023). "The inflammatory mediator, interleukin-6 (IL-6), is a remarkable inflammatory cytokine that is secreted by the immune cells or tumor cells that regulate the levels of CRP26, in addition to mediating the chemoresistance." (PMID 37258608, 2023). "For example, through IL-6 secretion, TAMs increase the capacity for carcinogenesis and tumor progression by controlling genes related to the cell cycle, angiogenesis, inflammation, and stem cell self-renewal promotion." (PMID 37958467, 2023). "The IL-6 receptor (IL-6R) antagonist tocilizumab (Toc) was applied to verify the role of IL-6/IL-6R signaling during tumor cell migration and invasion." (PMID 36614179, 2023). "While some of this interaction is hormone-related (i.e., increased production of leptin and estrogen), adipocytes are also able to secrete cytokines such as IL-6 and IL-8, which are known to increase both tumor initiation and metastatic spread." (PMID 36768435, 2023). "IL-6 was shown to be directly involved in tumor immunosuppression influencing the generation of myeloid-derived suppressor cells and tumorigenesis per se, being expected to be more pronounced with tumor progression." (PMID 38259646, 2023). "Previous works have described that the overexpression of IL-6 in tumor lines, such as MCF-7, induces the epithelial-mesenchymal transition and increases its invasiveness." (PMID 38137888, 2023). "CAFs are a key component of the tumor microenvironment and play a crucial role in promoting malignant progression by secreting various types of cytokines, including IL-6." (PMID 37481520, 2023).
tumor (continued). "MSCs can transform malignant cells in an IL-6 dependent manner questioning the interactions between MSCs and the tumor microenvironment which is most commonly very rich in IL-6." (PMID 36806993, 2023). "CD163+ TAMs drive the EMT process in primary CRC tumor cells through the IL-6/STAT3/miR-506-3p/Foxc1 axis, prompting CRC cell invasion to generate mesenchymal CTCs." (PMID 38129401, 2023). "It is noteworthy that the multifarious cytokine IL-6, which has been attributed tumor-promoting as well as anti-tumorigenic properties, was found to be strongly upregulated in TGCC tissue samples and cell culture models." (PMID 37174085, 2023). "The results were further confirmed by ELISA assay, in which, there was a lower level of IL‐6 in tumour lysates of KO mice than that in WT mice." (PMID 36419386, 2023). "They reported that benign prostate tissue had higher expression of IL-6 mRNA than matched patient tumor samples while TNFα expression remained unchanged." (PMID 36371231, 2022). "The results of logistic regression analysis showed that KPS scores, patient age, and IL-6 and IP-10 levels correlate with the clinical response after MRgFUS tumor ablation." (PMID 35053608, 2022). "IL-6 serum levels are increased with tumor development in patients with PCa and are higher in patients with metastasis." (PMID 35703345, 2022). "In the suggested model, paracrine IL-6 signalling from tumour cells also activated p-STAT3 and IL-6 expression in stromal components–namely endothelial cells, CAFs (cancer-associated fibroblasts), and myeloid cells." (PMID 36429126, 2022). "IL-6, a significant proinflammatory cytokine, was proved by accumulating evidences that it exerts a crucial role in tumor cell proliferation, colonization, angiogenesis, and bone metastasis." (PMID 36237303, 2022). "It has been reported that there is increased production of IL-6 in tumor tissues and in the serum of patients with CRC." (PMID 36286020, 2022). "The immunotherapeutic efficacy of the proposed vaccine approach (gDE7 + IL6-/- + 1MT) relied on the immune-cellular profile of the tumor microenvironment, including activation of myeloid cells and reduction of PMN-MDSC and Treg." (PMID 36405719, 2022). "The tumor IL-6 levels peaked at 8 h after treatment and rapidly decreased to baseline in subsequent time points." (PMID 36442099, 2022). "The increased IL-6 production from M2 and the elevated TGF-β generation from cancer-associated fibroblasts (CAFs) constitute the pro-tumor immunosuppressive microenvironment." (PMID 36612282, 2022). "Another component of the complex action of IL-6 is the NFkB transcription factor, which regulates immune processes and tumor-promoting inflammation." (PMID 35204748, 2022). "In lung cancer, iron-loaded TAMs enhance ROS production and pro-inflammatory cytokines (TNFα and IL6) to induce tumor cell death." (PMID 36158661, 2022). "Preoperative serum IL-6 higher than 10 pg/mL is a predictor of poor prognosis for survival, independent from tumor site, grade and stage in CRC patients." (PMID 35954156, 2022). "High expression of IL-6 in both tumor cells and surrounding tissues has been found in patients with HPV-16 and 18 infections." (PMID 36405719, 2022). "Our findings in HNSCC distinguished IL6 as a good prognostic biomarker, but lower expression level of IL6 was detected in tumor tissues compared to normal tissues." (PMID 35574984, 2022). "Tumor-secreted factors, such as IL-6 and TNF-α, have been proposed to inhibit lipogenesis and/or to promote lipolysis." (PMID 35319749, 2022). "Herein, DOX-PRNP2 ameliorated the elevated tumor levels of IL-6, TNF-α and VEGF more efficiently than free DOX." (PMID 35269343, 2022). "On the other hand, IL-6 is also suspected to play a role in tumour development and some groups have found a correlation between high circulating levels of IL-6 and poor prognosis in cancer patients." (PMID 36532027, 2022).
tumor (continued). "Intriguingly, IL-6, another early signature of 4T1 growth that we identified, cooperates with G-CSF to promote pro-tumour function of neutrophils." (PMID 35226704, 2022). "For example, signals from TNF-alpha, IL-17, and IL-6 appear to foster a tumor-supportive microenvironment, probably via mitogenic changes, which can impact epithelial cell migration and survival programs." (PMID 35563010, 2022). "It is known that cancer secretes the potent pro-inflammatory cytokines, TGF-beta, IL-6 and IL-8, that are able to recruit neutrophils, and drive a switch from an anti-tumor phenotype to a tumor-promoting and immunosuppressive profile." (PMID 36295558, 2022). "CAFs further secrete TGF-β and IL-6, which affect immune crosstalk and interfere with immune cell function to allow tumor cells to escape host immunity." (PMID 36544698, 2022). "In the third pattern, HER2, pSTAT3, and IL-6 are all co-localized in tumor cell clusters (Pattern 4), again suggesting potential autocrine IL-6 signaling in these regions." (PMID 35565421, 2022). "Again, samples obtained from whole tumor tissue show that abundant stromal IL-6 expression accompanies the 4T1-IL6-KO cells." (PMID 36142210, 2022). "It has therefore previously been concluded that increased systemic IL-6 levels are a result of local tumor production." (PMID 34023914, 2022). "Directly, IL-6 binds to its receptor on tumor cells and activates the STAT3 signaling pathway, which will lead to tumor progression through cyclin D1 and the proto-oncogene c-myc, an important regulator of the progression of G1 to S phase of the cell cycle." (PMID 36172343, 2022). "Inflammatory cytokines, such as interleukin-1, interleukin-6, and tumor necrosis factor α, not only promote angiogenesis, tumor growth but also impair cell-mediated immune response." (PMID 35797279, 2022). "Understanding the interaction between PD-L1 and IL-6 in the tumor immune microenvironment would provide novel insights of therapeutic strategies against CRC." (PMID 36362062, 2022). "IL-1β is secreted at the time of tumor initiation, and the level then decreases, but that of IL-6 rises." (PMID 35252445, 2022). "We therefore believe at least in 30200 and HGS2, a robust effect on reprogramming the tumor vasculature and immune surveillance following cediranib-therapy was achieved with a combination of anti-IL6 agents." (PMID 35313341, 2022). "Drosophila RasV12scrib−/− eye imaginal disc tumor cells secret IL-6 through tumor necrosis factor (TNF)‒JNK‒Fos pathway in response to TNF stimulation." (PMID 34459894, 2022). "For example, the expression of IL-6 expression is closely related to tumor stage, metastasis, and prognosis." (PMID 35069767, 2022). "Remarkably, Jagged1 promotes tumor growth by stimulating IL-6 release from osteoblasts, directly activating osteoclast differentiation and activity." (PMID 35646939, 2022). "Among the tumor hallmarks of UM angiogenesis, the IL6-JAK-STAT3 pathway has been well-described to promote cancer progression as well as immunosuppression in an autocrine manner." (PMID 35163491, 2022). "M2 TAMs mediate tumor immunosuppression through the secretion of immunosuppressive cytokines such as IL-1β, IL-6, IL-10, and TGF-β and suppress T cell immune responses through the expression of the immunosuppressive ligand PD-L1." (PMID 36092724, 2022). "Specifically, IL-6 constitutes a major promoter of tumor growth by activating the JAK/STAT3 pathway and by inducing oncogenic epithelial to mesenchymal transition (EMT)." (PMID 36077865, 2022). "In a mouse melanoma model, IDO inhibitor together with anti-tumor vaccine increased DC IL-6 secretion, Treg to Th17 conversion, and CD8+ T-cell activity and anti-tumor efficacy." (PMID 35371055, 2022). "The pro-angiogenesis effect of IL-6 is consistent with the inhibitory effect of probiotic supplements against tumor growth." (PMID 36452234, 2022).
tumor (continued). "The mechanism by which CD45RO+CCR6+CD4+ cells and granulocytes are recruited in TME is likely related to the presence of elevated amounts of IL-6 in tumor secretome from SD OSCC patients." (PMID 36713516, 2022). "This led to our focus on the role of microglia, tissue-resident macrophages of the CNS known to secrete soluble factors including IL-6, which can facilitate tumor growth and survival in a bidirectional crosstalk manner." (PMID 35159191, 2022). "Both IL-6 and TNF-α are associated with tumor development and metastasis, and the inhibition of tumor growth suppressors in people with cancer." (PMID 35699799, 2022). "iCAFs secrete IL-6 and other cytokines and share activation of the JAK/STAT pathway with tumor cells to cause ascites, promote tumor growth, and subsequently promote therapeutic failure." (PMID 35681617, 2022). "IL-6 collectively regulates the tumor proliferation target genes as inflammatory cytokines as TNF-α, and several angiogenic growth factors as VEGF." (PMID 35269343, 2022). "To further address the mechanism underlying type 3 immune cell and MDSC recruitment, we used CRISPR-Cas9 to knock out 4T1 tumor production of interleukin-6 (4T1-IL-6-KO), which functions in myelopoiesis, MDSC recruitment, and Th maturation." (PMID 36142210, 2022). "Collectively, these data suggest that expression of IL6/LIF in the tumor microenvironment is negatively correlated with response to AET." (PMID 36230597, 2022). "Western blot analyses were performed to assess the liver and corresponding tumor expression of inflammatory regulators, NF-κB, IL-6 and CRP, across the study groups." (PMID 36505796, 2022). "Within the tumor microenvironment IL-6 is produced by a multitude of cell types including tumor cells, immune cells, and stromal cells." (PMID 35844493, 2022). "M1 macrophages secrete proinflammatory cytokines such as tumor necrosis factor‐α (TNF‐α), IL‐12, and IL‐6, which promote tumor cell killing by activating T‐cells." (PMID 35612789, 2022). "Targeting IL-6 or IL-6 receptor (IL-6R) for tumor immunotherapy to block MDSC-mediated immunosuppression in cancer patients." (PMID 36263056, 2022). "Because IL-6 elicits several tumor growth-promoting effects including promotion of cancer cell migration, it is also a promising therapeutic target." (PMID 35089951, 2022). "On the other hand, there are considerable evidence that TAMs induce tumor chemotherapy resistance through the release of inflammatory cytokines and chemokines such as IL-6, CCL18, TNF-α, CCL2, and CXCR4." (PMID 36679900, 2022). "Contrary to expectations, Il6, a well-known marker for tumor progression, was expressed greater in the MyD88-/- group in the short-term experiment, in particular after LPS stimulation." (PMID 36224342, 2022). "ELISA was used to investigate the effects of EPA on serum cytokine production, including TNF-α, IFN-γ, IL-2, AST, BUN, and IL-6, in H22 tumor-bearing mice." (PMID 35597811, 2022). "CAFs exerted their influence on tumor or other stromal cells via direct cell–cell contact or releasing regulatory factors that remodel the microenvironment, such as TGFβ, IL-6, and PDGFs." (PMID 35610614, 2022). "Tumor proliferation and metastatic spread are promoted by neutrophils that are recruited by cancer-related chemokines and cytokines (e.g., IL-6 and TNF) which are highly present in advanced cancer patients and which are also associated with drug resistance." (PMID 35756636, 2022). "This seems particularly relevant, as IL-6 is produced not only by the immune system but also directly by the tumor, which makes cancer a unique and severe form of muscle loss and cachexia." (PMID 35847939, 2022). "The IL-6/sIL-6R complex can bind to gp130 on tumor cells, activate the JAKs and STAT3 signaling and promote tumor cell proliferation and prevent apoptosis." (PMID 35954156, 2022). "IL-6 produced in the tumor microenvironment by CSCs has been shown to enhance the neoplastic progression of tumors." (PMID 36627890, 2022).
tumor (continued). "In this analysis of a prospective imaging trial, we aimed to explore the role of IL-6 plasma levels during chemoradiation as a potential surrogate for PET imaging-based tumor hypoxia dynamics in HNSCC patients." (PMID 34773163, 2022). "The serum level of IL-12 was significantly higher in the tumor-bearing mice than in the tumor-free mice; moreover, the tumor-bearing mice also displayed a trend toward higher serum levels of IFNγ, IL-5, and IL-6." (PMID 35805045, 2022). "Multiple studies have pointed out that stromal and tumor cell-derived IL-6 plays an essential role in the generation and activation of MDSCs for SCCs." (PMID 35565378, 2022). "The dysregulated inflammatory profile observed here, in both PCa cell lines and PPAT when in co-culture, especially in the case of IL-6, has been shown to play a key role in the acquired pro-invasive effect by tumor cells." (PMID 35978404, 2022). "We found that spleen IL-6 levels were higher in low dose (5 mg/kg) (G2) and high dose (10 mg/kg) (G3) mematine groups when compared with tumor control group (G1) (p = 0.0204)." (PMID 36326318, 2022). "Using a cutoff value of 18.1 pg/mL for IL-6 in week 2, IL-6 concentration at this time point was able to predict tumor hypoxia response with a sensitivity of 80.0% and a specificity of 72.2%." (PMID 34773163, 2022). "In the animal study, it was also shown that the combined inhibition of IL-6 and PD-1 enhanced numbers of tumor infiltrating T lymphocytes." (PMID 36173644, 2022). "The IRE1α–XBP1 pathway was found to mediate IL-6 expression and subsequently support tumor cell proliferation in HCC." (PMID 35203283, 2022). "Further, those tumor cases harboring high level of IL-6 expression were frequently companied with high Glut5 expression." (PMID 35813468, 2022). "MDSCs are induced primarily by hepatic stromal cells through IL-6 signaling, and produce inhibitory enzymes to reduce T-cell immunity and promote hepatocellular carcinoma progression in the tumor microenvironment." (PMID 36362050, 2022). "The increase of IL-6 level is positively correlated with lymph node metastasis, tumor differentiation and vascular invasion of PC." (PMID 36591515, 2022). "It was notable that the IL11-induced secretome comprises key factors of the senescence associated secretory phenotype (SASP), including IL6, IL8 and CCL20, which are also important in the tumor microenvironment." (PMID 36012165, 2022). "The pro-inflammatory cytokines IL-6 and IL-11 are produced by multiple cell types within the tumor microenvironment, such as tumor-infiltrating immune cells, stromal cells and tumor epithelial cells." (PMID 35053592, 2022). "On the contrary, IL-32γ isoform is shown to diminish the levels of cytokines that promote tumor growth such as TNF-α, IL-1β, and IL-6, whereas the levels of IL-10 cytokine, a tumor growth-inhibiting cytokine, were elevated." (PMID 35281008, 2022). "IL-6, which shows the highest increase of >70-fold in xenografted versus the control plasma, has been shown to promote a microenvironment conducive to tumor growth." (PMID 36037073, 2022). "Enhanced IL-6 secretion is tightly correlated with the activation of ligand-mediated EGFR activation to promote the inflammatory tumor microenvironment of advanced-stage epithelial ovarian cancers." (PMID 36438839, 2022). "In contrast, M1 macrophages increase antigen presentation and enhance tumor cell clearance by secreting pro-inflammatory cytokines, including IL-6, IL-12, and TNF-α." (PMID 35625939, 2022). "Regarding immunomodulation, while IL-6 promotes the recruitment of myeloid-derived suppressor cells (MDSC) into the tumor microenvironment, it hampers Th1 lymphocytes infiltration, and dendritic cells activation." (PMID 36405719, 2022). "Specifically, in a preclinical model, we have previously shown that exercise mobilizes epinephrine‐sensitive NK cells to the circulation, which then infiltrate tumors by an IL‐6‐dependent mechanism leading to a reduction in tumor growth." (PMID 36199257, 2022).